BCORL1 (BCL6 corepressor like 1)
Description:
Transcriptional corepressor. May specifically inhibit gene expression when recruited to promoter regions by sequence-specific DNA-binding proteins such as BCL6. This repression may be mediated at least in part by histone deacetylase activities which can associate with this corepressor.
Synonyms: BCoR-L1; FLJ11362; CXorf10; SHUVER
Tractability: Antibody: its Gene Ontology location is reachable by antibodies, with high confidence. PROTAC: UniProt records ubiquitination sites on it; ubiquitination databases record sites on it.
Gene: Protein-coding gene on chromosome X (129,981,107 to 130,058,071, forward strand). Ensembl gene ENSG00000085185.
Subcellular location: Nucleus
Subcellular location (Human Protein Atlas): Nucleoplasm; Plasma membrane
Gene Ontology:
Molecular function: protein binding; transcription corepressor activity
Biological process: heterochromatin formation; negative regulation of DNA-templated transcription; negative regulation of transcription by RNA polymerase II
Cellular component: nucleoplasm; nucleus; chromatin; PRC1 complex
Gene-disease validity (ClinGen):
ClinGen rates the evidence that BCORL1 causes each of these diseases.
Shukla-Vernon syndrome (X-linked): Limited. A X-linked neurodevelopmental disorder manifesting in affected males with intellectual and learning disability, motor and language delay, autism spectrum disorder, attention deficit and hyperactivity disorder, and dysmorphic features.
Cancer hallmarks: invasion and metastasis (promotes)
Homologues: Orthologues: macaque BCORL1 (99% identical), chimpanzee BCORL1 (96% identical), pig BCORL1 (94% identical), guinea pig BCORL1 (92% identical), rat Bcorl1 (91% identical), mouse Bcorl1 (91% identical), dog BCORL1 (89% identical), rabbit BCORL1 (79% identical), tropical clawed frog bcorl1 (41% identical), zebrafish bcorl1 (19% identical), Drosophila melanogaster CG14073 (16% identical). Paralogues in human: BCOR (23% identical).